RNU6-313P (RNA, U6 small nuclear 313, pseudogene)
Gene: Small nuclear RNA gene on chromosome 7 (66,344,303 to 66,344,414, forward strand). Ensembl gene ENSG00000252126.
Homologues: Orthologues: chimpanzee U6 (100% identical), macaque U6 (89% identical), guinea pig U6 (76% identical), dog U6 (64% identical), rabbit U6 (61% identical), mouse Gm56122 (54% identical), rat LOC120095371 (53% identical). Paralogues in human: RNU6-797P (75% identical), RNU6-1145P (74% identical), RNU6-533P (74% identical), RNU6-59P (73% identical), RNU6-743P (73% identical), RNU6-1018P (72% identical), RNU6-1287P (72% identical), RNU6-38P (72% identical), RNU6-41P (72% identical), RNU6-838P (72% identical), RNU6-1005P (71% identical), RNU6-1157P (71% identical), and 1285 more.